FBN2 (fibrillin 2)
Diseases named in the same sentence as FBN2 in open-access papers (continued):
Sharing a sentence is not in itself a finding about the gene and the disease.
keloid (1 paper, 2020). An irregularly shaped, elevated mark on the skin caused by deposits of excessive amounts of collagen during wound healing. "The top 50 DEGs in lesional versus normal skin comparison included products related to fibrosis and cartilage/bone-differentiation (ADAM12, ASPN, COL10A1, COL11A1, FBN2), previously reported to be dysregulated in keloids." (PMID 33329590, 2020).
kidney cancer (1 paper, 2014). Primary or metastatic malignant neoplasm involving the kidney. "From this analysis 4 genes (FBN2, PCDH8, BNC1 and SFRP1) stand out as either particularly strong epigenetic biomarkers of kidney cancer or as significant predictors of patient outcome." (PMID 24454902, 2014).
lattice type I corneal dystrophy (1 paper, 2012). "Fibrillin-2, tenascin-C, matrilin-2, and matrilin-4 may be markers of the pathogenesis of either granular or lattice type I corneal dystrophy, as revealed by immunohistochemical analysis." (PMID 22876117, 2012). "Fibrillin-2, tenascin-C, matrilin-2, and matrilin-4 may be characteristic of the pathogenesis of either the granular or lattice type I corneal dystrophy, as revealed by immunohistochemical analysis." (PMID 22876117, 2012).
lupus nephritis (1 paper, 2026). Glomerulonephritis in the context of systemic lupus erythematosus. "Polymorphisms in HLA class II, TLR7 and FBN2 are notably linked to serious consequences, including lupus nephritis (LN)." (PMID 42123548, 2026).
meningioma (1 paper, 2023). A generally slow growing tumor attached to the dura mater. "Investigation of antigen distribution across all WHO grades yielded six common meningioma-associated antigens (A4GALT, FBN2, SNED1, MPP6, PCED1B, and ANGEL2)." (PMID 37368072, 2023).
muscular dystrophies (1 paper, 2015). "Here we present novel data that support the candidacy of FBN2 as a possible congenital muscular dystrophy gene as well as a potential pathogenetic pathway amenable to treatment protocols." (PMID 26114882, 2015). "Since contractures are a common feature of congenital muscular dystrophies, we analyzed Fbn2 null forelimb muscle at birth (P0 or P1), when contractures were most severe, and at P8, when contractures had resolved." (PMID 26114882, 2015). "First, the myopathy caused by the absence of fibrillin-2 in mice may be relevant to human congenital muscular dystrophies." (PMID 26114882, 2015).
Obesity (1 paper, 2025). Accumulation of substantial excess body fat. "Another GWAS found that the genes FBN2, LINC01122, and RGS6, which relate to obesity, are also linked to sleep activity in children." (PMID 40024983, 2025).
periodontitis (1 paper, 2023). An acute or chronic inflammatory process that affects the tissues that surround and support the teeth. "These were the periodontitis risk gene ABCA1, FBN2 (fibrillin 2), and MAPK6 (mitogen-activated protein kinase 6)." (PMID 37822091, 2023).
pulmonary arterial hypertension (1 paper, 2020). Pulmonary arterial hypertension (PAH) is a group of diseases characterized by mean pulmonary artery pressure >20 mmHg and elevated pulmonary arterial resistance leading to right heart failure. "Similar work in human heart samples from patients with pulmonary arterial hypertension identified key genes that change uniquely in RV failure, including increased FBN2 (which had a similar trend in our model), and CTGF (which was significantly increased in our model, FDR < 0.05)." (PMID 31960631, 2020).
respiratory failure (1 paper, 2015). The significant impairment of gas exchange within the lungs resulting in hypoxia, hypercarbia, or both, to the extent that organ tissue perfusion is severely compromised. "On a C57Bl/6 background, Fbn2 null mice showed severe defects in musculature, leading to neonatal death from respiratory failure." (PMID 26114882, 2015).
squamous cell carcinoma (1 paper, 2025). A carcinoma arising from squamous epithelial cells. "ML identified robust predictive models, highlighting SUV and kurtosis (from PET and CT features, respectively) and the expression levels of TP63, EPHA10, FBN2, and IL1RAP as key tools for distinguishing adenocarcinoma from squamous cell carcinoma." (PMID 40192792, 2025).
syndactyly (1 paper, 2022). A disease characterized by the presence of syndactyly, including syndromic and non-syndromic forms. "Moreover, it is noteworthy that mice lacking Fbn2 display a limb-patterning defect (syndactyly), due to the impaired balance between chondrogenic outgrowth and interdigital cell death, which are under the control of several signaling molecules, including BMPs." (PMID 35910214, 2022).
tumor (23 papers, 2013 to 2025). "For example, the expression of FBN2 was positively correlated with M0 macrophages, indicating its potential role in regulating the immune response in the tumor microenvironment." (PMID 40612061, 2025). "The pan‐cancer analysis showed the difference in FBN2 expression between normal tissues and several types of tumours." (PMID 37337404, 2023). "Recently, some studies have found a possible link between FBN2 and some types of tumours, including colorectal adenocarcinomas and non‐small‐cell lung cancer." (PMID 37337404, 2023). "The patients were divided into high FBN2 expression and low FBN2 expression groups, and the survival curve, clinical characteristics, tumour microenvironment (TME), and immune cell differences were analysed between the two groups." (PMID 37337404, 2023). "In these cancers, except for PCPG, PRAD, KIRC, and KICH, FBN2 is highly expressed in tumour tissues, including BLCA." (PMID 37337404, 2023). "FBN2 exposure in tumor endothelium can affect TGF-β by affecting microfibril isolation which directly stimulates tumor angiogenesis, resulting in higher local activity of TGF in the tumor microenvironment concentration." (PMID 36245981, 2022). "Nonetheless, we decided to focus on 4 TSGs (TFPI2, SOX17, GATA4, and FBN2) because we later confirmed that these genes had a cancer-specific methylation pattern in primary OSCC tumor samples." (PMID 31405379, 2019). "The top-ranked gene set was the extracellular matrix structural constituent gene set and the top-ranked gene within this was FBN2 (Fibrillin-2), which has been proposed previously as a marker for tumour methylation by Yagi et al10." (PMID 23096130, 2013). "For BLCA, the differential FBN2 expression in all tumour tissues and normal tissues had a statistical significance with a p value less than 0.001, and in 19 tumour tissues and corresponding normal tissues also had a statistical significance with a p value less than 0.01." (PMID 37337404, 2023). "Likewise, TGF-beta binding (TB) domain superfamily (LTBP1, LTBP2, FBN2; p = 4.76e-06) was over-represented in upregulated tumor ECM proteins." (PMID 35340765, 2022). "Moreover, the exposure of fibrillin-2 in the tumor endothelium directly induces tumor angiogenesis by affecting TGF-β sequestering by microfibrils, which results in the higher TGF-β concentration in the TME." (PMID 36534225, 2022). "FBN2 is a tumor suppressor in cancer and is frequently silenced by promoter methylation." (PMID 30139993, 2018). "Additionally, it also has been demonstrated that FBN2 might serve as tumour‐suppressive effects and is a characteristic basement membrane marker in several types of cancer." (PMID 37337404, 2023). "Besides, it also has been proved that FBN2 might both have tumor-suppressive effects and is a typical basement membrane marker in several types of cancers." (PMID 35991839, 2022). "A number of fast evolving, placental genes show tumorigenic or tumor suppression activity (ADAM12, ADAMTS18, CAPN6, EGFL6, HTRA4, LIN28B) and others are involved in disorders associated with epithelial and connective tissues (FBN2) or have immune functions (IL1RL1, PRG2, SIGLEC6)." (PMID 26641094, 2015). "Among these genes, six genes are potential regulator of tumor metastasis, including CEMIP, FBN2, TIAM1, ITGA2, ARHGAP42, and GPRIN3." (PMID 38971758, 2024). "Overexpressed in tumor matrix were proteins involved in ECM organization such as LOX, LAMB3, ADAMTSL1 and FBN2." (PMID 35340765, 2022).
tumor (continued). "In the favorable ccrcc2_3 subtypes, miR-204-5p was strongly upregulated, predicted long OS, and repressed several targets that are involved in tumor invasiveness and metastasis (MMP3, MMP9, AURKB, FBN2, ITGB4, SPDEF)." (PMID 32915890, 2020). "Four genes (TFPI2, SOX17, GATA4, and FBN2) satisfied the criteria of “cancer-specific methylation” with high-frequency methylation in cell lines, no/undetectable methylation in normal oral mucosa, and frequent methylation in primary OSCC tumor samples." (PMID 31405379, 2019). "The result is conclusive because a polymorphic CA repeat located outside the FBN2 gene retained heterozygosity in this tumor, showing that FBN2 was not affected by the microdeletion." (PMID 26634009, 2015).
cancer (19 papers, 2014 to 2025). A tumor composed of atypical neoplastic, often pleomorphic cells that invade other tissues. "This may suggest that FBN2 is a risk factor in these cancers." (PMID 37337404, 2023). "As integral components of microfibrils, which provide strength and elasticity to the extracellular matrix, fibrillins, particularly FBN-1 and FBN-2, are thought to be involved in cancer pathogenesis and maintenance of the pluripotency of embryonic stem cells." (PMID 29042385, 2017). "In our study, the Pan‐cancer analysis for FBN2 was first performed." (PMID 37337404, 2023). "In particular, FBN2, is an obvious candidate for the targeted hypermethylation of this chromosomal region because mutations in the gene have been linked to Marfan-like syndromes and because hypermethylation has been reported as a biomarker in CRC and other cancers." (PMID 26634009, 2015). "Thus, the genes LOXL3, ADAM19, FBN2, and RND3 are associated with cancer relevant biological processes such as loss of adhesion, proliferation, migration and metastasis and are therefore might be functionally related to CLIP2 in the context of radiation induced PTC-carcinogenesis of PTC." (PMID 32727620, 2020). "Fibrillin 2 (FBN2) is an extracellular matrix protein, and the transcription elongation regulator 1-like (TCERG1L) gene is located on chromosome 10 and has recently been shown to have frequent cancer-specific methylation according to our microarray-based approaches." (PMID 33946400, 2021).
connective tissue disorder (14 papers, 2010 to 2025). A disease involving the connective tissue. "FBN1, FBN2, and FBN3 encode the human fibrillins and mutations in FBN1 and FBN2 cause connective tissue disorders called fibrillinopathies, affecting cardiovascular, dermal, skeletal, and ocular tissues." (PMID 35910214, 2022). "Mutations in FBN1 and FBN2 cause connective tissue disorders called fibrillinopathies." (PMID 35910214, 2022). "It is well known that mutation of FBN2 leads to dominant heritable connective tissue disorders." (PMID 32771030, 2020). "The fibrillinopathies, a diverse group of connective tissue disorders, are caused by pathogenic variants in FBN1 and FBN2 genes." (PMID 39273357, 2024). "These two similar syndromes are heritable connective tissue disorders in an autosomal dominant manner caused by mutations in two genes: FBN1 and FBN2, respectively." (PMID 37962692, 2024). "Mutations in human FBN1, FBN2, LTBP2, LTBP3 and LTBP4 have been associated with connective tissue disease in humans." (PMID 24703491, 2014). "Congenital contractural arachnodactyly is a genetic connective tissue disorder that involves a defect in the FBN2 gene with resultant decreased production and/or impaired function of fibrillin-2." (PMID 34466327, 2021).
myopathy (4 papers, 2015 to 2024). A disease of the muscle in which the muscle fibers do not function properly. "This genetic approach provided further evidence that activated BMP signaling caused the Fbn2 null myopathy, including both the reduction in muscle mass and the increase in fat that infiltrates the forelimb muscle." (PMID 26114882, 2015). "Fibrillin-2 null mice are born with myopathy and contractures and demonstrate accumulation of white fat during the early postnatal period." (PMID 26114882, 2015). "If activated BMP signaling contributes to myopathy and infiltrating fat, then modulating the fibrillin-2/BMP interaction may be a clever therapeutic strategy." (PMID 26114882, 2015). "Similar approaches could be used to identify the genetic modifier(s) in 129 vs. C57/Bl6 mice controlling severity of the Fbn2 myopathy." (PMID 26114882, 2015). "Hence, poor muscle architecture and the specific replacement of muscle tissue with fat were similar in Fbn2 null mice on 129/Sv and C57/Bl6 backgrounds, but the myopathy was less severe on the 129/Sv background." (PMID 26114882, 2015).
genetic disorders (2 papers, 2023 to 2024). "A number of potential OA GWAS effector genes have been identified, including some that have been implicated in Mendelian diseases with joint and skeletal abnormalities, such as BICRA (also known as GLTSCR1), EIF6, CHST3, and FBN2." (PMID 37579195, 2023).
immune system diseases (2 papers, 2015 to 2023). "Importantly, FBN2 has been found to be associated with immune system diseases as a single gene." (PMID 38200810, 2023). "Specifically, eight genes (IRF5, UBA7, TMTC1, GSTM3, FBN2, OAS1, PODXL, ITGA2) were previously associated with immune system diseases in at least one study." (PMID 25874939, 2015).
infection (2 papers, 2010 to 2024). The state of being infected such as from the introduction of a foreign agent such as serum, vaccine, antigenic substance or organism. "We identified fibrillin-2-like isoform X1 (fbn2) in this study, a structural constituent of extracellular matrix, mapped to focal adhesion and showed a 2.9-fold increased abundance during infection." (PMID 39292008, 2024).
lip (1 paper, 2025). "Novel loci include those mapping to LHX8 and TSBP1 (combined clefts), ARHGEF18 and ARHGEF19 (cleft lip with/without palate), FBN2 (cleft lip only), SLC35B3 (cleft palate only), CASC20 (Pierre Robin Sequence) and CHRM2 (non-syndromic cleft palate only)." (PMID 41075272, 2025).
retinopathy (1 paper, 2023). "Here we investigated the efficacy and molecular mechanism of intravitreally applied fibrin-2 recombinant protein in mice with fbn2-deficient retinopathy." (PMID 37100863, 2023). "We therefore conducted this study to explore the effect and molecular mechanism of intravitreally injected fbn2 recombinant protein for the treatment of fbn2-deficiency retinopathy." (PMID 37100863, 2023). "The observations suggest that intravitreally applied fbn2 recombinant protein reversed the retinopathy caused by an fbn2 knockdown." (PMID 37100863, 2023). "In conclusion, the intravitreal application of AAV-sh-fbn2 led to an fbn2 deficiency-related retinopathy in mice." (PMID 37100863, 2023). "We developed an AAV-knockdown fbn2-deficiency retinopathy mouse model by intravitreally applied AAV-sh-fbn2 (adeno-associated virus for expressing short hairpin RNA for fibrillin-2), and then injected the fbn2 recombinant protein in various doses." (PMID 37100863, 2023). "On this basis, this study aimed to investigate the therapeutic effect of FBN2 recombinant protein on FBN2-deficient retinopathy, to provide theoretical basis for targeted intervention of gene defective retinopathy." (PMID 37100863, 2023). "It has been reported that the FBN2 protein is located in Bruch's membrane, that it is reduced in AMD eyes, and that a reduction in the expression of fbn2 in the retina was associated with the development of a retinopathy in mice." (PMID 37100863, 2023). "Our study suggested that human recombinant protein pairs can improve the symptoms of fbn2-deficient retinopathy in mice, suggesting that the functional domain of fbn2 may be located in the homology of the FBN2 gene of mice and human being." (PMID 37100863, 2023). "Second, the model of genetically a fbn2 deficiency-associated retinopathy may differ from the fbn2 deficiency-related retinopathy in patients." (PMID 37100863, 2023). "The effect of exogenously supplied fbn2 recombinant protein on fbn2-deficiency-related retinopathy was not known." (PMID 37100863, 2023). "In the case of the fbn2 deficiency retinopathy, it would thus be reasonable to substitute the lacking fibrillin-2 protein by an intravitreally applied recombinant protein." (PMID 37100863, 2023). "The signs of this retinopathy could be partially reversed by the repeated intravitreal application of the fbn2 recombinant protein." (PMID 37100863, 2023). "In our experimental study, the intravitreal injection of AAV-sh-fbn2 led to the development of a retinopathy characterized by fundus exudation with multifocal lesions in the deep retinal layers and retinal pigment epithelium, parallel to a reduction in the ERG amplitudes." (PMID 37100863, 2023).
FBN2 also shares sentences with these, for which no sentence is quoted: aortic aneurysm (3 papers); Diabetes (3); esophageal squamous cell carcinoma (3); arthrogryposis (2); hyperphosphatemia (2); Hypocalcemia (2); intracranial aneurysms (2); Osteopenia (2); thoracic aortic aneurysm (2); adenocarcinoma (1); aneurysm (1); Aortic dissection (1); aortic stenosis (1); Areflexia (1); Bardet-Biedl syndrome (1); Camptodactyly (1); cardiovascular disease (1); Carney complex variant (1); cerebral cavernous malformation 1 (1); Cognitive impairment (1); congenital myopathy (1); congestive heart failure (1); corneal dystrophies (1); coronary artery disease (1); diabetic retinopathy (1); dilatation (1); ectopia lentis (1); emphysema (1); equinovarus (1); geleophysic dysplasia (1).
A further 27 diseases each share a sentence with FBN2 in 1 paper.